LINC01544 (long independently transcribed non-coding RNA 1544)
Synonyms: TCONS_00026194
Gene: Long non-coding RNA gene on chromosome 18 (61,747,971 to 61,758,464, forward strand). Ensembl gene ENSG00000260440.
Diseases named in the same sentence as LINC01544 in open-access papers:
LINC01544 is named in the same sentence as 1 disease in open-access papers, as found by Europe PMC text mining. Sharing a sentence is not in itself a finding about the gene and the disease. The quoted sentences say what the papers report.
cancer (1 paper, 2024). A tumor composed of atypical neoplastic, often pleomorphic cells that invade other tissues. "The potential for participation in cancer-associated processes decreases in a set of LINC00667, LINC00668 > LINC00470 > LINC01926, LINC01544, LINC01909, depending on the number of functional terms." (PMID 38540157, 2024). "Finally, there is a subset of LINC01378, LINC01443, LINC01477, and LINC01544, which are typically represented in one or two pathways in only one cancer type." (PMID 38540157, 2024).